FH (fumarate hydratase)
Diseases named in the same sentence as FH in open-access papers (continued):
Sharing a sentence is not in itself a finding about the gene and the disease.
tumor (continued). "This rare low-grade form of FH-deficient RCC overlaps with succinate dehydrogenase (SDH)-deficient RCC and a variety of other low-grade eosinophilic renal tumors, further increasing the difficulty of differential diagnosis of this tumor." (PMID 39659780, 2024). "Conversely, FH expression was lost in the majority of tumor cells." (PMID 38793008, 2024). "In addition, in most cancers, TOMM40 and FH expression differed significantly between tumor tissue and normal paracancerous tissue." (PMID 38285218, 2024). "As tumor suppressors, SDH and FH are mutated to lose their enzymatic activity." (PMID 38169635, 2024). "Tumor cells displayed 2SC positivity with simultaneous positive immunostaining for the FH protein." (PMID 38721148, 2024). "This indicates that there may be a relation between FH expression and the efficacy of tumor immunotherapy; however, the specific mechanism remains unclear." (PMID 38398104, 2024). "While immunohistochemical detection of FH protein remains crucial for diagnosing HLRCC, some HLRCC tumor cells may still express FH protein." (PMID 38974045, 2024). "Our univariate analysis for overall survival showed that older age (≥65 years) (p = 0.02), advanced tumor invasiveness (p < 0.01), nodal metastasis (p = 0.02), distant metastasis (p < 0.01), and low s-FH-Ab levels (p < 0.01) are significant poor prognostic factors." (PMID 38791507, 2024). "Bevacizumab + erlotinib should be used for most FH mutant tumours (consensus; LE: 2b; GR: B)." (PMID 38594593, 2024). "Immunohistochemistry showed absence of FH in the tumor epithelium, indicating a FH-deficient RCC, which additionally supported PAX8+/panCK+." (PMID 39282017, 2024). "It is unclear whether the equivalent levels of aspartate 1100 and 0011 in the tumors reflects a small amount of residual FH activity in tumor cells, or whether part of the aspartate pool in these samples was taken up from other tissues with functional FH." (PMID 37611583, 2023). "Interestingly, FH-associated tumorigenesis is enhanced by the activation of well-known proto-oncogenes, such as MYC, and suppression of tumour suppressors, including PTEN." (PMID 37689804, 2023). "In contrast, suc-ado and suc-cys levels correlated with FH-deficient RCC and tumor burden." (PMID 37259915, 2023). "However, there are not so many reports on the relationship between the enhanced activity of fumarate hydratase and tumor growth." (PMID 38139831, 2023). "For CSGs for which germline-focused tumor analysis was recommended only for specific cancer types and age groups, the proportion of variants meeting these recommendations was approximately 1%–4%, except for POLE (22%) and FH (20%)." (PMID 37916805, 2023). "FH-deficient RCC is highly malignant and can metastasize when the tumor volume is very small." (PMID 37076922, 2023). "Since other than tumor resection there is no effective therapy for metastatic FH-deficient RCC, an accurate method for early diagnosis is needed." (PMID 37053010, 2023). "To define the role of these proteins on tumor growth, we knocked down fH in CMT cells using shRNA." (PMID 36686777, 2022). "In sum, PDAC patients with FH amplification might mean more favorable prognosis because of lower blood glucose and more cDC infiltration in tumor microenvironment." (PMID 36434634, 2022). "Of note, analysis of the somatic mutations of the tumor did not reveal any other pathogenic variants in the FH gene but revealed an LOH pattern." (PMID 35034951, 2022).
tumor (continued). "To illustrate whether lower FH expression promote tumor cell proliferation through regulating the glucose metabolism, we detected glycolytic rate, glucose consumption, oxaloacetate, and lactate production." (PMID 36434634, 2022). "The early diagnosis of tumour FH genetic defects could be clinically detected by IHC of the protein or by metabolomics investigations to search for specific fumarate accumulation." (PMID 34070384, 2021). "We identified a novel variant (c.1256C>T (p.S419L)) in a patient with this phenotype and the pathogenicity of this variant was supported by the lack of staining of the tumor sample with FH antibody on immunohistochemistry." (PMID 34439371, 2021). "Of particular interest, one recent study revealed that tumor metabolites, including 2-hydroxyglutarate, fumarate hydratase, and α-ketoglutarate, hindered DNA repair by disrupting local chromatin signaling, demonstrating the importance of metabolism in DNA repair activity." (PMID 33902615, 2021). "More importantly, we explored the relationship between FH expression and various tumor immunities." (PMID 34737838, 2021). "It indicated that TGFβ1‐treated MDA‐MB‐231 cells had a strong tumor formation ability and FH could significantly inhibit the growth of TNBC xenograft tumor in zebrafish." (PMID 32037729, 2020). "Fumarase, also known as Fumarate hydratase (FH), is a mitochondrial tumor suppressor." (PMID 32774303, 2020). "Hence, owing to mutations in FH, SDH and L2HGDH genes, which lead to TET and KMDs inhibition, aberrant accumulation of oncometabolites occurs in RCC, stimulating tumor growth and aggressiveness." (PMID 30986931, 2019). "Considering his age at onset and family history of skin disease and uterine myoma, and tumor histology, HLRCC was suspected, and thus he and his family underwent germline FH mutation testing, which demonstrated the presence of mutation in FH exon 5 (c.688A > G, p.Lys230Glu)." (PMID 31182090, 2019). "A few studies have reported FH expression in various tumor cells." (PMID 30987235, 2019). "It should be noted that TC-RCC is a rare and indolent tumor that should not be confused with fumarate hydratase (FH)-deficient RCC, where the tumor shows a low grade tubulocystic pattern and with abrupt transition to high-grade infiltrative carcinoma." (PMID 31905821, 2019). "Additionally, mutations of FH, SDH, and IDH1/2 cause increased production of reactive oxygen species (ROS), either directly by mutated SDH or indirectly in tumor cells with mutant IDH1/2 and FH." (PMID 28748451, 2018). "Western blotting indicated that protein expression of FH was markedly depleted in tumor tissues." (PMID 30062063, 2018). "Several mechanisms have been proposed to explain how FH functions as a tumor suppressor." (PMID 29456767, 2018). "However, the tumour risks in SDHB mutation carriers are significantly less than originally thought and so there is (as in FH mutation carriers) a tension between over-investigation and early detection." (PMID 29680948, 2018). "Recent data have shed new light on the mechanisms of the tumor suppressor effect of FH and SDH." (PMID 28092669, 2017). "Mitochondrial TCA cycle enzymes, such as succinate dehydrogenase (SDH) and fumarate hydratase (FH), could function as mitochondrial tumour suppressors." (PMID 28373964, 2017). "IDH1 or -2 mutations were found in 60.8% of the central cartilaginous tumours, while mutations in FH and SDH were absent." (PMID 28484589, 2017). "Because of their central role in the acquisition of tumour hallmarks by SDH- and FH-deficient cells, succinate and fumarate are now referred to as “oncometabolites”, as 2-hydroxyglutarate, the organic acid generated by mutant isocitrate dehydrogenase mutants in gliomas and acute myeloid leukaemia." (PMID 28471419, 2017).
tumor (continued). "Moreover, a connection between cancer and altered metabolism was clearly established when mutations in genes encoding for the two TCA cycle enzymes succinate dehydrogenase (SDH) and fumarate hydratase (FH) were identified in human tumours." (PMID 27083002, 2016). "Somatic mutations in cancer driver genes, tumor suppressors, and amplified oncogenes such as EGFR, RAS, BRAF, MYC, isocitrate dehydrogenase (IDH), and fumarate hydratase (FH) have been shown to be linked to specific alterations in metabolic activity in cancer cells (11, –, 14)." (PMID 26023239, 2015). "As expected, we confirmed the FH and NF1 mutations in corresponding tumours." (PMID 25625332, 2015). "Our results demonstrate distinct loss of 5hmC in tumor cells in SDH- and FH-deficient tumors." (PMID 26472283, 2015). "Mutations of FH and SDH cause the inactivation of prolyl hydroxylase (PHD), resulting in the stabilization of HiFs and driving the transcriptional activation of genes supporting tumor growth, neovascularization, invasion and metastasis." (PMID 24348776, 2014). "In this framework, it is interesting that two key enzymes of the TCA cycle, namely FH and SDH (complex II of the respiratory chain) are de facto tumor suppressor genes whose loss-of-function mutations provide a permissive environment for oncogenic hits to trigger transformation." (PMID 24280190, 2013). "In the last ten years, dominant defects associated with oncogenesis were described in cytoplasmic and mitochondrial isoforms of three nuclear-encoded enzymes, SDH, FH, and IDH, allowing to investigate the extrametabolic roles of the TCA cycle metabolites and their signaling to tumor formation." (PMID 22888353, 2012). "Genetic analysis of tumor samples indicates that FH acts as a tumor suppressor gene." (PMID 22087286, 2011). "Moreover, 15/32 patient samples (47%) demonstrated a greater than twofold reduction in FH mRNA levels in tumor samples relative to normal control." (PMID 21695080, 2011). "IDH1, encoding two TCA enzymes, fumarate hydratase (FH) and succinate dehydrogenase (SDH), has been found to sustain loss-of-function mutations in certain human tumors, which likewise contribute to tumor growth via stimulating the HIF-1a pathway and mutationally altering metabolic enzymes." (PMID 20459648, 2010). "Although germline mutations in genes encoding the mitochondrial enzymes succinate dehydrogenase and fumarate hydratase are associated with neoplasia, these disorders do not show phenotypic overlap with FHC/fRDD." (PMID 20140240, 2010). "The tumor suppressor concept was further underlined by the observation, that the leiomyomata showed virtually no FH enzyme activity." (PMID 19949549, 2009). "The identification of FH as a tumor suppressor was an unexpected finding and following the identification of subunits of succinate dehydrogenase in 2000 and 2001, was only the second description of the involvement of an enzyme of intermediary metabolism in tumorigenesis." (PMID 18366737, 2008). "Two enzymes in the TCA cycle enzymes, SDH and FH, are found to be tumor suppressor genes." (PMID 19057672, 2008). "The mechanism by which FH can act as a tumour suppressor is unclear." (PMID 12177782, 2002). "This evidence led to the belief that FH deficiency could be involved in more complex genetic changes in the tumor, rather than be a key factor in driving uLMS." (PMID 40002168, 2025). "Somatic mutations in the FH gene occur within the cells of the tumor itself and are not inherited." (PMID 40002168, 2025). "Despite aggressive treatment, the disease progressed rapidly, and discussions regarding genetic testing could not take place during his lifetime, although circulating‐tumor DNA showed mutation of FH gene." (PMID 40034895, 2025). "However, recent data has shown that senescence is not a feature of FH loss in immortalised epithelial kidney cells and, despite not being senescent, these cells cannot form tumours in vivo." (PMID 37689804, 2023).
tumor (continued). "Moreover, as FH-deficient tumour models and HLRCC samples show an inflammatory response, these tumours may benefit from PD1/PDL1 inhibitors." (PMID 37689804, 2023). "Moreover, many unique mutations were only found in CSF samples, but not in the tumor tissue and plasma samples, which includes FH mutation, SETD2 mutation, WT1 mutation, CDKN2A mutation, CDKN2B mutation." (PMID 36937524, 2023). "Finally, tumours in the kidney capsule have been only observed when injecting FH-deficient cells but not in autochthonous models of FH loss." (PMID 37689804, 2023). "Furthermore, the discovery of mutations in mitochondrial enzymes of the tricarboxylic acid (TCA) cycle, such as succinate dehydrogenase (SDH), fumarate hydratase (FH), and isocitrate dehydrogenase 1, and 2 suggests that mitochondrial dysfunction enhances tumor growth or promotes cancer progression." (PMID 35269393, 2022). "Finally, we examined changes in the tumor microenvironment in the setting of fH knockdown." (PMID 36686777, 2022). "However, the current research on the role of FH in tumor immunity is still limited." (PMID 34737838, 2021). "Indeed, analysis of two FH-deficient cell lines—UOK 262 and NCCFH1—as well as FH-deficient tumor, showed strong succination of various, functionally important proteins, including glyceraldehyde 3-phosphate dehydrogenase (GAPDH) and Kelch-like ECH-associated protein 1 (Keap1)." (PMID 31963199, 2020). "The EMT-linked mechanisms involving reduced SDH activity may share similarities with the action of other mitochondrial tumor suppressors, such as fumarate dehydrogenase, fumarate hydratase, and isocitrate dehydrogenase, as well as OXPHOS defects that contribute to tumor development." (PMID 31164982, 2019). "Accumulating evidence shows that genetic mutations in cancer-driver genes, tumor suppressors, and amplified oncogenes are linked to specific alterations in metabolic pathways in cancer cells, involving proteins such as isocitrate dehydrogenase (IDH), fumarate hydratase (FH), MYC, K-RAS and BRAF." (PMID 30369878, 2018). "Pseudo-hypoxia may be achieved through inactivation of tumor-suppressor genes, such as the von Hippel–Lindau (VHL) tumor suppressor, E3 ubiquitin ligase gene (VHL); the genes associated with the succinate dehydrogenase (SDH) complex (the SDHx genes); and the fumarate hydratase (FH) gene." (PMID 27047799, 2016). "Interestingly, this paradox has been brought into even sharper focus by the striking mutational profiles that do exist in very specific 'metabolic’ tumor suppressor genes (that is, FH and SDH) that are inactivated in specific rare cancer syndromes, and in the IDH1 and 2 oncogenes." (PMID 24491179, 2014). "However, mutations in FH do not explain sporadic CLM formation in scar tissue, since aberrant FH expression or somatic mutations are not seen in sporadic tumours." (PMID 22799750, 2012). "Additionally, fumarate hydratase (FH) encodes a protein that is an enzymatic component of the tricarboxylic acid (TCA) cycle and its deactivating mutations lead to high level of HIF-1α and tumor formation." (PMID 20824128, 2010). "Functional enrichment analysis of the identified proteins revealed that fumarate hydratase (FH), a component of the TCA cycle, functions as a tumor suppressor and catalyzes the conversion of fumarate to succinate malic acid." (PMID 41380966, 2025). "The tumor cells showed expression of PAX8, CA9, AMACR/P504S, Vimentin, CK7, CD10, FH, INI1(SMARCB1) and ELOC(TCEB1), and ELOC was mainly located in the nucleus." (PMID 41306531, 2025). "Genetic defects in FH can lead to elevated fumarate levels, which stabilize HIF-1α and activate pathways that promote angiogenesis, further linking it to tumor progression." (PMID 40034261, 2025). "Immunophenotype (Primary Tumor): 2SC (+), CAIX (+), CD10 (-), CK (+), EMA (+), FH (+), Ki-67 (30% in hotspots), TFE3 (-), CK20 (-)." (PMID 40678055, 2025).
tumor (continued). "Specifically, FH deletion suppresses AMPK activation to further cross‐activate mTOR and ACC thus promoting lipid biosynthesis to provide energy material for tumor growth." (PMID 39584783, 2024). "Still, as HLRCC tumours are rare and there is a lack of genetic information, it is unknown whether these oncogenic events occur due to additional genetic mutations, or if they are a direct consequence of FH loss." (PMID 37689804, 2023). "The researchers identified several circulating metabolites that correlated with FH-mutant RCC and tumor size." (PMID 37259915, 2023). "Both FH and SDH can be regarded as tumor suppressors, as the deposition of succinate and fumarate promotes the proliferation of cells, usually directed towards similar targets." (PMID 37109219, 2023). "Functional experiments revealed the role of FH in altering tumor glucose metabolism and in impacting PDAC tumor microenvironments." (PMID 36434634, 2022). "Importantly, the cells overexpressing the FH mutant exhibited higher proliferation and extracellular acidification rate value (ECAR) which might be caused by the upregulated HIF-1α indicating the tumor phenotype." (PMID 35163394, 2022). "Together, FH has contradictory cellular functions, as it is pro-survival through its role in the TCA cycle and functions as a tumor suppressor in tumorigenesis." (PMID 36428601, 2022). "The effects of fumarate in chromatin remodeling and DNA damage are not tumor specific, because the DNA hypermethylation observed in HepG2 cells exposed to millimolar concentrations of fumarate were comparable to the hypermethylation detected in FH deficient cells." (PMID 34065551, 2021). "Hypoxic tumor cells have upregulated expression of C3-C3a-C3aR axis and downregulated CD55, CD46, and FH, which play important roles in tumor cell proliferation and CSCs stemness maintenance." (PMID 33869223, 2021). "Intriguingly, tumor cells have been reported to harbor genetic alterations in enzymes involved in the TCA cycle such as succinate dehydrogenase (SDH) and fumarate hydratase (FH)." (PMID 34777681, 2021). "Two enzymes, fumarate hydratase (FH) and succinate dehydrogenase (SDH) mediate the metabolism of fumarate and succinate in the TCA cycle and are considered as tumor suppressors." (PMID 30283496, 2018). "Succinate dehydrogenase (SDH) and fumarate hydratase (FH) are tricarboxylic acid (TCA) cycle enzymes and tumor suppressors." (PMID 26472283, 2015). "A bi-allelic inactivation of FH has been detected in almost all HLRCC tumors, and therefore FH was suggested to function as a tumor suppressor." (PMID 20231875, 2010). "Absent FH IHC staining in tumor cells is highly specific for FH-RCC, but its sensitivity is limited." (PMID 40678055, 2025). "The multivariate analysis demonstrated that FH expression retained a highly significant effect on the angiogenesis score (p = 1.97 × 10−14), independent of age, tumor size, or molecular subtype." (PMID 41008787, 2025). "Pioneer studies have shown that HELLS acts as a tumor suppressor and influences cellular metabolism, such as lactate production or the regulation of tricarboxylic acid (TCA) cycle intermediates through its control of fumarate hydratase expression." (PMID 40175344, 2025). "Additionally, in this case, tumor cells don’t express CD117, TFE3, HMB45, or SDHB, but express FH and INI1(SMARCB1)." (PMID 41306531, 2025). "TRIM47 was identified as a negative regulator of FH expression in ICC cells and tumor tissues." (PMID 41380966, 2025). "Additional immunohistochemical examination showed that tumor cells were negative for FH and positive for 2SC, and the final pathological diagnosis was FHD‐RCC." (PMID 40034895, 2025).